NOL4L (nucleolar protein 4 like)
Synonyms: C20orf112; C20orf113; dJ1184F4.2; DKFZP566G1424; dJ1184F4.4
Tractability: PROTAC: its protein half-life has been measured.
Gene: Protein-coding gene on chromosome 20 (32,443,059 to 32,585,333, reverse strand). Ensembl gene ENSG00000197183.
Subcellular location (Human Protein Atlas): Nucleoplasm
Gene Ontology:
Molecular function: protein binding
Cellular component: nucleoplasm
Genetic constraint (gnomAD): Loss-of-function variants: 5 observed, 56.2 expected, observed/expected ratio (o/e) 0.089, 90% interval 0.045 to 0.19. The upper end of that interval is the gene's LOEUF score, 0.19, which puts it in group 1 of 6, group 1 being the genes least tolerant of losing a copy. Missense variants: 668 observed, 923.94 expected, observed/expected ratio (o/e) 0.72, 90% interval 0.68 to 0.77. Synonymous variants: 409 observed, 386.4 expected, observed/expected ratio (o/e) 1.06, 90% interval 0.98 to 1.15.
Homologues: Orthologues: chimpanzee NOL4L (100% identical), macaque NOL4L (99% identical), pig NOL4L (98% identical), dog NOL4L (98% identical), mouse Nol4l (96% identical), rabbit NOL4L (96% identical), rat Nol4l (96% identical), guinea pig NOL4L (82% identical), tropical clawed frog nol4l (42% identical), zebrafish nol4lb (41% identical). Paralogues in human: NOL4 (54% identical).
Diseases named in the same sentence as NOL4L in open-access papers:
NOL4L is named in the same sentence as 10 diseases in open-access papers, as found by Europe PMC text mining. Sharing a sentence is not in itself a finding about the gene and the disease. The quoted sentences say what the papers report.
leukemia (3 papers, 2021 to 2025). A malignant (clonal) hematologic disorder, involving hematopoietic stem cells and characterized by the presence of primitive or atypical myeloid or lymphoid cells in the bone marrow and the blood. "It is also noteworthy that the expression of Nol4l (C20orf112), a gene associated with B-cell lymphoma and leukemia, was significantly reduced in both mutant clones." (PMID 41299498, 2025). "Kataegis occurred particularly frequently at a per-sample level between chr20:31050000-31080000 which corresponds to the region of NOL4L/C20orf112 (chr20:31,030,862-31,071,385) a known fusion partner of RUNX1 and PAX5 in leukaemia." (PMID 33632293, 2021).
neuroblastoma (3 papers, 2022 to 2025). Neuroblastoma (NB) is the most common solid, extracranial childhood tumor. "Two recent neuroblastoma studies revealed the involvement of NOL4L including circPDE5A/miR-362-5p/NOL4L axis and circ_0132817/miR-432-5p/NOL4L axis." (PMID 41327336, 2025). "The study determined the relationship between miR‐676‐3p, CASC11, and NOL4L based on bioinformatics tools and found that high expression of NOL4L reversed the effects of CASC11 on neonatal neuroblastoma, including inhibition of proliferation or proliferation." (PMID 35592755, 2022).
nicotine dependence (1 paper, 2015). Physical and psychological dependence on nicotine. "A SNP in C20orf203, near to NOL4L, but independent of our sentinel variant, has previously been implicated in nicotine dependence." (PMID 26423011, 2015).
tumor (5 papers, 2020 to 2025). "Recent research has shown that it sequesters miR-29 from nucleolar protein 4 like (NOL4L), increasing NOL4L expression and stimulating tumor progression." (PMID 38891878, 2024). "Inhibition of circ_0132817 restrained tumor growth by upregulating miR-432-5p and downregulating NOL4L, suggesting that circ_0132817 knockdown inhibits the progression of NB through the modulation of the miR-432-5p/NOL4L axis." (PMID 36672544, 2022). "Furthermore, there were six genes (EGR1, MUC20, MUC3A, NBPF19, NOL4L, and OR4L1) that were simultaneously mutated in the tumor tissues and junction tissues." (PMID 33133167, 2020).
adenocarcinoma (1 paper, 2019). A common cancer characterized by the presence of malignant glandular cells. "Adenocarcinoma-derived SKOV3 cells partially expressed both the CCC-related marker CPNE8 and the HGSC-related marker NOL4L." (PMID 31487856, 2019).
NOL4L also shares sentences with these, for which no sentence is quoted: acute lymphoblastic leukemia (1 paper); acute myeloid leukemia (1); B-cell lymphoma (1); cancer (1); colorectal cancer (1).